PERP (p53 apoptosis effector related to PMP22)
Diseases named in the same sentence as PERP in open-access papers (continued):
Sharing a sentence is not in itself a finding about the gene and the disease.
cervical cancer (2 papers, 2013 to 2026). A primary or metastatic malignant neoplasm involving the cervix. "From the genes differentially expressed between early and advanced stages of cervical cancer, six genes – three upregulated (BCL3, IGF2, and PIK3R1) and three downregulated (PTPN4, PERP, and DUSP1) were selected for validation by qRT-PCR." (PMID 24403257, 2013).
colorectal cancer (2 papers, 2016 to 2023). A primary or metastatic malignant neoplasm that affects the colon or rectum.
papilloma (2 papers, 2018 to 2024). A benign epithelial neoplasm that projects above the surrounding epithelial surface and consists of villous or arborescent outgrowths of fibrovascular stroma. "It has been demonstrated that mice lacking PERP in the skin exhibit resistance to papilloma development, displaying fewer and smaller papillomas compared to wild-type mice." (PMID 39201982, 2024).
Salmonella Infections (2 papers, 2019). Infections with bacteria of the genus SALMONELLA. "Recently it was shown that PERP accumulates at the apical PM in response to Salmonella infection due to alterations in its uptake and degradation." (PMID 31508245, 2019). "PERP, and other eleven Salmonella SipC-interacting proteins were first found involved in Salmonella infection." (PMID 31565575, 2019). "In addition, PERP participates in the integrity of epithelial cells and pro-inflammatory pathways by inducing PMN migration and caspace-3 activation during Salmonella infection." (PMID 31565575, 2019).
squamous cell carcinoma (2 papers, 2010 to 2024). A carcinoma arising from squamous epithelial cells. "In a UVB-induced squamous cell carcinoma model, PERP deficiency has been observed to promote both tumor initiation and progression." (PMID 39201982, 2024). "Similarly, human squamous cell carcinomas exhibit a loss of PERP expression yet retain adherens junctions, suggesting a relevant stage in cancer development." (PMID 39201982, 2024). "Similarly, human squamous cell carcinomas display loss of PERP expression with retention of adherens junctions components, indicating that this is a relevant stage of human cancer development." (PMID 20975948, 2010).
actinic keratosis (1 paper, 2021). A precancerous lesion of the skin composed of atypical keratinocytes. "In addition, the expression of PERP is downregulated in most invasive SCC but not in actinic keratosis, indicating that loss of PERP is an early event in oral carcinogenesis." (PMID 34203070, 2021).
Autoimmunity (1 paper, 2013). The occurrence of an immune reaction against the organism's own cells or tissues. "The relevance of anti-PERP autoimmunity to the pathophysiology of PV is underscored by the fact that PERP knockout mice display a phenotypic similarity to PV." (PMID 23505434, 2013).
cervical tumor (1 paper, 2022). "According to our previous RNA-seq data, CASP7, EMC6 and PERP were upregulated in cervical tumor tissues, which seemed to conflict with the qPCR results of SFTA1P knockdown." (PMID 36344495, 2022).
COVID-19 (1 paper, 2024). A disease caused by infection with severe acute respiratory syndrome coronavirus 2.
dermatomycosis (1 paper, 2023). Superficial infections of the skin or its appendages by any of various fungi. "Therefore, the PERP gene should be included in the list of inheritance diseases that cause dermatomycosis, which consequently will help in the establishment of effective treatment strategies." (PMID 37510397, 2023).
erythrokeratoderma (1 paper, 2023). An umbrella term for a group of rare genetic skin disorders characterized by well-demarcated plaques of reddened, dry and thickened skin. "We report a patient with recessive erythrokeratoderma (EK) in which whole exome sequencing (WES) prioritized by human phenotype ontology (HPO) terms revealed the presence of the novel variant c.153C > A in the N-terminal region the PERP gene." (PMID 37510397, 2023).
esophageal cancer (1 paper, 2010). A primary or metastatic malignant neoplasm involving the esophagus. "Indeed, previously published expression profiling studies suggest that PERP may be one in a group of key predictors for patient treatment response in esophageal cancers." (PMID 20975948, 2010).
fungal infections (1 paper, 2023). "Similar to our patient, a recent article described two unrelated families with the ichthyosis phenotype and active fungal infections with two novel homozygous variants in PERP gene." (PMID 37510397, 2023).
glioma (1 paper, 2020). A benign or malignant brain and spinal cord tumor that arises from glial cells (astrocytes, oligodendrocytes, ependymal cells). "Next, we used the TCGA dataset to investigate the correlations between miR-7156-3p expression levels and HOXD13 or PERP expression levels in glioma." (PMID 33162825, 2020). "TCGA dataset analysis showed that the miR-7156-3p expression level was negatively correlated with the HOXD13 expression level in glioma but not with the PERP expression level, suggesting that HOXD13 may be a major target of miR-7156-3p in glioma." (PMID 33162825, 2020).
head and neck squamous cell carcinoma (1 paper, 2021). A squamous cell carcinoma that arises from any of the following anatomic sites: lip and oral cavity, nasal cavity, paranasal sinuses, pharynx, larynx, and salivary glands. "Loss of PERP expression in nonneoplastic epithelial cells adjacent to the surgical margin in patients with head and neck squamous cell carcinoma (HNSCC) is associated with a higher risk of local recurrence." (PMID 34203070, 2021).
meningioma (1 paper, 2017). A generally slow growing tumor attached to the dura mater. "AQP1, FRZB, PDGFRL, and PECAM1 were consistently underexpressed in meningioma samples; MEDAG, MYC, PAMR1, PDPN and PERP were consistently overexpressed in nearly every meningioma sample by both measurements." (PMID 29073243, 2017).
Palmoplantar keratoderma (1 paper, 2023). Abnormal thickening of the skin of the palms of the hands and the soles of the feet. "After step-wise bioinformatics WES analysis and subsequent prioritization using the HPO term “Palmoplantar keratoderma” (HP:0000982), a novel homozygous variant in the PERP gene (NM_022121.5) was identified: c.153C>A, p.(Cys51Ter)." (PMID 37510397, 2023). "Several genes have been associated with PPK including PERP, a gene encoding a crucial component of desmosomes that has been associated with dominant and recessive keratoderma." (PMID 37510397, 2023). "To date, seven pathogenic variants in the PERP gene have been described in nine unrelated families with keratoderma." (PMID 37510397, 2023). "Our results, therefore, support the existence of a recessive form of PERP-associated EK and PPK primarily related with milder dermatological symptoms compared to the more severe dominant form of keratoderma." (PMID 37510397, 2023).
pancreas adenocarcinoma (1 paper, 2022). "Next, we utilized tumor tissue microarrays (TMAs) to query PERP expression in tumor samples from 200 unique pancreas adenocarcinoma patients." (PMID 34874916, 2022).
pancreatitis (1 paper, 2022). Inflammation of the pancreas. "Individuals with low expression exhibited a modestly reduced, but significant, rate of patient-reported pancreatitis (22.0% versus 38.9%, P = 0.0187) when compared with patients with higher PERP expression." (PMID 34874916, 2022).
pituitary tumours (1 paper, 2019). "A recent study revealed that PERP is lost in more aggressive sparsely granulated human growth hormone pituitary tumours, and its loss and associated desmosomal instability may be an early driver of tumour progression." (PMID 31892336, 2019).
pulmonary arterial hypertension (1 paper, 2024). Pulmonary arterial hypertension (PAH) is a group of diseases characterized by mean pulmonary artery pressure >20 mmHg and elevated pulmonary arterial resistance leading to right heart failure. "miR-629-5p has been shown to be upregulated in the plasma of patients with pulmonary arterial hypertension and also in hypoxic pulmonary artery smooth muscle cells, promoting vascular remodeling via FOXO3 and PERP." (PMID 39201485, 2024).
serous ovarian carcinoma (1 paper, 2015). "We have previously documented the utility of Nutlin-3a in low-grade serous ovarian carcinoma, with up-regulation of cell cycle control, and apoptosis genes including CDKN1A, CDKN2A, PERP, and PUMA." (PMID 26248031, 2015).
somatotrophinomas (1 paper, 2019).
cancer (33 papers, 2008 to 2026). A tumor composed of atypical neoplastic, often pleomorphic cells that invade other tissues. "Further investigation of the potential diagnostic and prognostic value of PERP expression in human cancers represents an exciting avenue to pursue." (PMID 20975948, 2010). "PERP inhibitors are widely used for ATM-expression-deficient cancers." (PMID 35740635, 2022). "The findings have also broad-ranging implications for other cancers in which similar overall dysfunction of p63 may underlie the regulation of apoptosis effectors such as PERP and the impaired ability of tumour cells to engage in apoptosis." (PMID 27584665, 2016). "PERP-deficiency promotes cancer by enhancing cell survival, desmosome loss, and inflammation." (PMID 22673103, 2012). "Pan-cancer analysis revealed that PERP expression differed significantly between tumor and normal tissues across various cancer types." (PMID 41164195, 2025). "Considering its relatively high risk estimate within the final gene set, its elevated expression in LUAD and other malignancies, and literature support for its roles in cancer biology, PERP was prioritized for in vitro functional assays." (PMID 41164195, 2025). "The significant differences in expression between precancerous and benign tumors (PERP: 72.8% vs. 26.6%, p = 0.001; Akt: 37.7% vs. 0.9%, p = 0.001) further highlight their involvement in the transition from benign to malignant neoplasms." (PMID 39201982, 2024). "PERP is localized to desmosomes, and alterations in PERP function have been shown in various cancer types." (PMID 39201982, 2024). "The loss of KDM6A can reduce the expression of certain cancer suppressor genes, such as CDKN1A and PERP." (PMID 36052737, 2022). "Expression of PERP is downregulated in numerous cancers, suggesting that PERP is a tumor suppressor protein." (PMID 35955749, 2022). "PERP was concomitantly independently identified as a protein that was downregulated in several human cancers, suggesting that PERP acts as a tumor suppressor." (PMID 32843065, 2020). "This study suggests that the loss of PERP and desmosomes promotes cancer through specific mechanisms rather than general changes in differentiation status." (PMID 34203070, 2021). "LGALS1, NPM1, RACK1, and PERP were upregulated from ductal to cancer cells." (PMID 34326696, 2021). "Notably, and PERP expression was higher in precancerous than in malignant tumors." (PMID 39201982, 2024). "A possible explanation to this contradiction is that the increased transcriptional level of PERP might be a feedback to a decreased protein level of PERP or to an inhibition of the downstream effector of PERP in this cancer, but future studies are required to solve this problem." (PMID 33748143, 2021). "However, METTL14 overexpression did not impact cancer cells overexpressing PERP with a 3′-UTR mutation." (PMID 32843065, 2020).
cancer (continued). "When performing pairwise comparisons among the different stages of cancer, stage IV patients had increased expression of FGA, FGB, PERP, GPR107, CDH3 compared to controls." (PMID 39146279, 2024). "In Pt2, five integrations with total frequencies of more than 1% were observed near or in cancer-related genes (DPP4, TNFAIP3/PERP, MLLT10, EPS8, and SPINT1)." (PMID 34786435, 2021). "In Pt2, one integration located between two cancer-related genes, TNFAIP3 and PERP, yielded increased expression of both genes with statistical significance; however, this integration was due to LASN, indicating integration only in peripheral T cells." (PMID 34786435, 2021). "Endogenous PERP mRNA and protein levels were determined in five UM cell lines (92-1, MEL202, OCM-1, MEL 285 and MEL290) and ARPE-19 (as a non-cancer reference cell line)." (PMID 27584665, 2016). "In addition to human orthologs previously identified as playing key roles in OSCC, p63 signaling, and other cancers, namely, FAT2, K14, and PERP, we identified several novel regulators, including Cotl1, Bcam, Adipor2, and Wnt7b." (PMID 36672394, 2023). "However, we noticed that the ACSN model does not contain the PERP gene, which is consistent with the fact that the ACSN database is focused on cancer pathways." (PMID 35696426, 2022).
tumor (28 papers, 2010 to 2026). "In oral squamous cell carcinoma (OSCC), loss of PERP is related to increased tumor aggressiveness and worse local control." (PMID 34203070, 2021). "Deficiency of PERP has been shown to promote tumor growth, whereas ZW10 is essential in mitotic checkpoint control." (PMID 30071870, 2018). "The results provide novel insights into the mechanisms underlying the apoptotic resistance in tumours with reduced PERP expression." (PMID 27584665, 2016). "In HER2− tumours, baseline expression of 48 genes associated with poor antiproliferative response (p < 0.005) including PERP and YWHAQ, the two most significant, and the transcription co-regulators (SAP130, HDAC4, and NCOA7) which were among the top 16 most significant." (PMID 31892336, 2019). "Functional experiments further confirmed that KRT8 and PERP promote tumor proliferation and migration, providing new insights into their roles as therapeutic targets." (PMID 39895784, 2025). "Visualizing the mRNA expressions of CCER2 and PERP in spatial coordinates, we observed that the co-expression of these genes was more common in the epidermal compartment compared to the tumor core." (PMID 41131107, 2025). "While PERP acts as a pro-apoptotic and tumor-suppressive molecule, Akt acts as a pro-survival and oncogenic kinase." (PMID 39201982, 2024). "Studies have shown that it can inhibit tumor growth by activating IL-24/PERP and suppressing atypical TGFβ signaling." (PMID 38097551, 2023). "Six key genes were located within malignant tumor cells and enriched predominantly in the cytoplasm of tumor cells, including PERP, BAK1, VDAC1, FOXO3, AKT3, and IGF1." (PMID 36900213, 2023). "This process is also mediated by restoration of transcription and translation of PERP, which is inactive or significantly downregulated in UM primary tumours and in UM cell lines (current study)." (PMID 27584665, 2016). "The expression of PERP is significantly downregulated at the transcriptional and protein level in the aggressive, highly metastatic monosomy 3-type UM tumours compared with disomy 3-type UM tumours." (PMID 27584665, 2016). "However, the upregulation of PERP in epiMCC cells also suggested a potential suppressive effect on tumor growth, underscoring the intricate interplay between MCC cells and the epidermal microenvironment." (PMID 41131107, 2025).